RAD50 (RAD50 double strand break repair protein)
Diseases named in the same sentence as RAD50 in open-access papers (continued):
Sharing a sentence is not in itself a finding about the gene and the disease.
pituitary adenoma (1 paper, 2022). "Interestingly, correlation between CN and expression was also apparent for the M6 pituitary adenoma, with RAD50 overexpression correlating with CN gain, and BRCA1 expression loss correlating with CN loss." (PMID 35978432, 2022).
pneumonia (1 paper, 2017). An acute, acute and chronic, or chronic inflammation focally or diffusely affecting the lung parenchyma, caused by an infection in one or both of the lungs (by bacteria, viruses, fungi, or mycoplasma.).
polycystic ovary syndrome (1 paper, 2017). A disorder that manifests as multiple cysts on the ovaries. "A recent genome-wide association study (GWAS) of polycystic ovary syndrome (PCOS) in European cohorts has identified six susceptibility loci mapping to 11q22.1 (YAP1), 2p21 (THADA), 11p14.1 (FSHB), 2q34 (ERBB4), 12q21.2 (KRR1), and 5q31.1 (RAD50)." (PMID 28195137, 2017).
prostate tumor (1 paper, 2017). "Concerning CTAGE5-KHDRBS3, SDK1-AMACR, and RAD50-PDLIM4 gene fusions Ren proven their occurrence also in the additional 54 prostate tumor samples analysed (with percentages ranging from 24 to 37%)." (PMID 28114882, 2017).
psoriasis (1 paper, 2015). An autoimmune condition characterized by red, well-delineated plaques with silvery scales that are usually on the extensor surfaces and scalp. "Within these loci, specific variants including chromosome 2q31.2 (rs62176107), chromosome 5q33.1 (rs17728338), and within RAD50 on chromosome 5q33.3 (rs6596086) demonstrate opposing effects on risk of AD and psoriasis." (PMID 25574825, 2015). "AD and psoriasis represent opposing extremes of Th2 cell dysregulation, and therefore we hypothesize that RAD50 polymorphisms might exert opposing effects on AD and psoriasis through variation in DNA repair resulting in a differential skew in Th2 cell response." (PMID 25574825, 2015). "The most highly significant variant maps to RAD50 (MIM 604040, rs6596086, ORADfull = 1.17, ORPSOfull = 0.88, p = 6.3 × 10−7); this variant is associated with increased risk of AD but is protective against psoriasis." (PMID 25574825, 2015). "However, RAD50 mRNA shows significantly increased expression in psoriasis lesional skin and a trend to reduced expression in AD lesional skin." (PMID 25574825, 2015).
pterygium (1 paper, 2021). A wedge-shaped fibrovascular lesion arising from the bulbar conjunctiva and extending to the cornea. "It was previously reported that genes involved in double-strand DNA break repair, RAD50, RAD51, XRCC2 and XRCC3, are differentially expressed in pterygium." (PMID 34769520, 2021).
Rotavirus infection (1 paper, 2025). Infection with any of the rotaviruses. "Rotavirus infection relocalizes the MRN complex to the cytoplasm through the viral NSP2 and NSP5 proteins, and retrovirus HTLV-1 p30 interacts with Rad50 and NBS1 to sequester and disrupt the formation of the MRN complex on DSBs foci." (PMID 40008889, 2025).
sarcoma (1 paper, 2025). A usually aggressive malignant neoplasm of the soft tissue or bone.
serous cystadenoma (1 paper, 2017). A serous neoplasm in which the cysts and papillae are lined by a single layer of cells without atypia, architectural complexity or invasion. "Our finding is consistent with results of a previous study that demonstrated a reduced detection of MRE11, RAD50, and NBS1 in cancer tissue by immunohistochemistry as compared to the control group of healthy ovaries and serous cystadenomas." (PMID 28073364, 2017).
Telangiectasia (1 paper, 2023). Telangiectasias refer to small dilated blood vessels located near the surface of the skin or mucous membranes, measuring between 0.5 and 1 millimeter in diameter. "Histological analysis in rad50Δ2/+ medaka showed an association between rad50 and telangiectasia." (PMID 37098078, 2023).
Turner syndrome (1 paper, 2017). Turner syndrome is a chromosomal disorder associated with the complete or partial absence of an X chromosome. "Eight TFs and four ERFs are among the differentially expressed genes, as well as eight genes associated with Turner syndrome (PROCR, NR3C1, INSR, APOB, BMP15, F8, IL6, and WAS) and two genes that are haploinsufficient in humans (RAD50 and SLC33A1)." (PMID 28818098, 2017).
uterine cancer (1 paper, 2020). Primary or metastatic malignant neoplasm involving the uterine corpus and/or the cervix. "Rad50 mRNA expression was upregulated in almost all cancer types except uterine cancer." (PMID 32111912, 2020).
Werner syndrome (1 paper, 2009). "Significant age-related methylation alterations in telomere maintenance gene-loci TERT, ERCC1, RAD50, and the Werner syndrome gene-locus (WRN) were also observed." (PMID 19680444, 2009).
cancer (117 papers, 2004 to 2026). A tumor composed of atypical neoplastic, often pleomorphic cells that invade other tissues. "SIC-19 decreases the ability of cancer cells to repair homologous recombination by blocking the phosphorylation of the RAD50-Ser635 site, which makes cancer cells more susceptible to PARPis." (PMID 40612876, 2025). "The role of RAD50 variants for the risk of cancer, however, is less clear, and more case–control real‐life data are essential for the risk evaluation." (PMID 41031707, 2025). "The potential value of RAD50 missense variants is exemplified by a previous case report of synthetic lethality to DNA damage checkpoint inhibition in combination with DNA‐damaging chemotherapy in cancer cells harboring the RAD50*p.L1237F variant." (PMID 41031707, 2025). "We also examined homozygous Rad50-D69Y and Rad50-L1237F mutants, which model recurrent mutations in human cancer affecting residues in the Walker A and B ATPase motifs, respectively." (PMID 39185212, 2024). "RAD50, part of the MREll complex, influences the predisposition to cancer due to its complex interactions with various oncogenes such as ATM, BRCA1, and CHK2." (PMID 38213474, 2023). "In conclusion, the most common germline, heterozygous alterations found in cancer patients affect NBN in Slavic European populations, and occur less frequently in other populations worldwide with a frequency similar to RAD50 variants (~0.2% cancer patients)." (PMID 36982687, 2023). "IHC also indicated that low RAD50 is associated with poor outcomes/more progressed cancer–lower BCSS, high-grade, high-risk NPI and high mitotic index." (PMID 34782604, 2021). "Based on our data, we propose a model for the allosteric regulation of Rad50 ATP hydrolysis that describes how each of these mutations disrupt ATM signaling in cancer cells." (PMID 31889185, 2020). "In the two validated cohorts, increased RAD50 expression was observed in cancer tissues compared to that in para-cancer tissues, which was shown be associated with decreased OS and DFS." (PMID 32922536, 2020). "Mouse knockouts of RAD50 are embryonic lethal, and, like CHEK2, RAD50 mutations are associated with cancer risk." (PMID 30305041, 2018). "In conclusion, current results demonstrate that RAD50/MRE11 variants occur at very low frequency in analyzed group of cancer patients in Poland." (PMID 24079363, 2013). "These two genes, considered of moderate penetrance, such as RAD50, can contribute to inherited cancer by altering DNA repair mechanisms, increasing the risk of accumulation of genetic mutations and, ultimately, the risk of cancer development in certain individuals." (PMID 40259910, 2025). "Our data thus provide evidence for the functional diversity of RAD50 missense variants which may translate into a differential response to cancer treatment with therapeutics that cause DNA damage and/or cell division defects, respectively." (PMID 41031707, 2025). "To demonstrate whether the RAD50 mutation identified in our patient contributed to the development of cancer, we generated and analyzed medaka with mutations in the corresponding exon of the rad50 gene as that in the patient." (PMID 37098078, 2023). "Our finding that destabilization of Rad50 induced by loss of INPP4B may reveal the Achilles’ heel of certain cancers." (PMID 32341333, 2020). "However, heterozygous carriers of mutations in Mre11, Rad50, Nbs1/Nbn have only a small increase in cancer incidence over the lifecourse." (PMID 32954257, 2019).
cancer (continued). "It seems that pathogenic variants of the RAD50 gene may have a impact to cancer development only in certain populations, like Finnish." (PMID 24079363, 2013). "Notably, Rad50 was a DNA repair protein that, in hypomorphic mutants, revealed a predisposition toward cancer, loss of spermatogenic stem cells and loss of hematopoietic stem cells." (PMID 21569470, 2011). "Using lentiviral constructs, we investigated whether cancer‐related RAD50 missense variants can complement the delayed damage response after exposure to the chemotherapeutic agent epirubicin and/or mitotic progression in RAD50‐deficient fibroblasts." (PMID 41031707, 2025). "Materials and Methods: Families harbouring PVs in RAD50, RAD51C, RAD51D, and BRIP1 were identified by analysing a cancer-predisposing genes panel using Ion S5 system technology." (PMID 40282418, 2025). "RAD50 has been described as a predictive factor for the success of chemotherapy in several different cancers, largely deduced from the analysis of RAD50 transcript levels or the presence of loss‐of‐function variants." (PMID 41031707, 2025). "MRE11 and RAD50, which are involved in dsDNA repair, are mutated by frameshift mechanisms in their microsatellite loci in MSI cancer subsets." (PMID 40573300, 2025). "Targeting RAD50 is a chemotherapy-sensitive approach to cancer therapy in the context of chemotherapy resistance." (PMID 40995126, 2025). "In the KEGG pathway enrichment analysis data demonstrated that; homologous recombination, ERBB signaling pathway, cell cycle, PI3K-Akt signaling pathway, microRNAs in cancer and pathways in cancer were associated with RAD21, RAD50 and BARD1." (PMID 37474724, 2023). "Defects in MRE11A/RAD50/NBS1 (MRN) genes and overexpression of the MRN proteins are both linked to cancer, generating confusion about how the MRN complex impacts cancer initiation and progression." (PMID 37509263, 2023). "Another report on this cancer found that the interaction of RAD50 (recombinant) with Mre11 and Nbs1 leads to G2/M cell cycle arrest through decreased DSBs, inhibits colony formation, and promotes sensitivity to radiation." (PMID 34900673, 2021). "Six pathogenic variants (in BRCA1,BMPR1A,FANCA,FANCC,NBN genes) with cancer related phenotype and three unsolicited variants (in BRCA2,PALB2,RAD50 genes) were reported to patients." (PMID 31937788, 2020). "As a result of this finding, RAD50, NBS1, and MRE11 were added to the MSKCC IMPACT (Integrated Mutation Profiling of Actionable Cancer Targets) gene list." (PMID 32187176, 2020). "Our study reveals that elevated RAD50 expression is significantly correlated with cancer progression and poor survival in HBV-related HCC patients." (PMID 32922536, 2020). "Targeting DNA repair proteins such as Rad50 in cancer cells would offer great advantages over conventional radiotherapy or chemotherapy." (PMID 32341333, 2020). "The goal of this study was to query this database and map all MRE11, RAD50 and NBS1/NBN mutations appearing in cancer cells." (PMID 33339169, 2020). "The data presented here highlights differences in the evolution of MRE11, RAD50 and NBS1/NBN and identify key mutation hotspots within cancer samples." (PMID 33339169, 2020).
cancer (continued). "Here we identify mutation hotspots in MRE11, RAD50, NBS1/NBN, and CtIP from analyzed cancer data on COSMIC." (PMID 33339169, 2020). "We found in this cancer, RAD50, involved in homologous recombination of DNA, as a novel poor prognostic marker." (PMID 30345029, 2018). "A series of publications have shown that suppression of homologous recombination repair by HDACi treatment, including SAHA and homologous recombination associated RAD50 and MRE11 suppression, were observed in cancer cells only." (PMID 29414878, 2018). "Control group tumors exhibited sustained growth following cancer cell injection (-b), between days 1 and 14, IR combined with Ad-RAD50 infection significantly regressed the tumor growth compared with IR alone (P = 0.018)." (PMID 26951044, 2016). "They found that Zscan4c co-operates with Rad50 and Mre11 to maintain the telomere length by homologous recombination as found in some cancer cells." (PMID 25772165, 2015). "In the selected fragments of the RAD50 and MRE11 genes, which have been reported to harbor mutations in cancer, we were unable to confirm the occurrence of the formerly known mutations in our group of either ALL or AML cases." (PMID 24093751, 2013). "Without irradiation (open symbols), the fraction of Rad50 foci-positive nuclei in the hypersensitive cells (40%) was also apparently higher than in control (26%) or in cells from cancer patients with normal reaction to RT (15%)." (PMID 15150571, 2004). "The mean amounts of the Rad50 protein (open symbols) were almost the same in nonirradiated cells derived from healthy subjects (1.0±0.2), cancer patients with normal (0.8±0.2) and increased clinical reaction (1.0±0.2)." (PMID 15150571, 2004). "In order to further characterise the observed increase of the fraction of Rad50 foci-positive nuclei in cells derived from hypersensitive cancer patients, we quantified the formation of Rad50 foci by counting their number per nucleus." (PMID 15150571, 2004). "In contrast, the irradiated cells of hypersensitive cancer patients revealed a slightly increased Rad50 level of 1.1±0.1, which was 1.3 times higher than in irradiated control cells (0.8±0.2)." (PMID 15150571, 2004). "At 2 h postirradiation, the expression of Rad50 decreased by about 20% in cells from healthy donors and from cancer patients with normal reaction to RT." (PMID 15150571, 2004). "However, RAD50 loss‐of‐function has repeatedly been linked with resistance to cytostatic agents, and RAD50 is regarded as one of the major contributors to cancer resistance toward chemotherapeutic drugs." (PMID 41031707, 2025). "Identified monoallelic variants in genes linked to autosomal recessive predisposition to cancer such as the ones in RAD50, FANCC, and FANCM might also be relevant for cancer risk." (PMID 35250968, 2022). "Finally, our analysis of DEGs associated with low expression of MRE11, RAD50 and NBS1 identified increased expression of seven genes associated with mitochondrial dysfunction and metabolic reprogramming in cancer." (PMID 34782604, 2021). "Other mutated cancer genes included those involved in Wnt signaling (APC, AMER1), mitogen signaling (KRAS, BRAF), epigenetic modification (ARID1A, ARID2, DNMT3A, NCOA3) and DNA repair (RAD50, BRIP1, ERCC5, RECQL4)." (PMID 33776923, 2021). "POLE and RAD50 mutations were identified as independent prognostic indicators regardless of cancer type and MMR status." (PMID 33960179, 2021). "Interestingly, we found four genes (FXR1, RAD50, SP100, SMC6) mutated in 50% of the G1 LS-cancer samples, with the latter three belonging to the APB branch of the ALT-TMM pathway." (PMID 31750255, 2019). "Additionally, the authors showed that vorinostat suppressed the DNA repair proteins, MRE11 and RAD50, in only the cancer cells, collectively leading to cancer cell death." (PMID 29651407, 2018).